STAT3 (signal transducer and activator of transcription 3)
Diseases named in the same sentence as STAT3 in open-access papers (continued):
Sharing a sentence is not in itself a finding about the gene and the disease.
tumor (continued). "MiR-21-5p may be activated by the phosphatidylinositol-3-kinase (PI3K), signal transducer and activator of transcription 3 (STAT3), and programmed cell death factor 4/tumor necrosis factor-α (PDCD4/TNF-α) signaling pathways, which affect inflammatory processes and tumor progression in CRC." (PMID 38584226, 2024). "In response, the sustained activation of IRE1α and ATF6 branches driven by MEK/ERK pathway endows tumor cells with enhanced survival capacity, with the involvement of the activation of downstream autophagy, mitochondrial fission, mitophagy and JAK/ STAT3 pathway." (PMID 38291473, 2024). "In addition to the tumor invasive role, enrichment analysis revealed the overexpressed ELF4 was involved in the immune regulation, characterized by the elevated activity of Il6/Jak/Stat3 signaling, interferon alpha (IFN-α) response, and IL2/Stat5 signaling." (PMID 39132148, 2024). "Notably, pSTAT3 expression in primary tumor biopsy samples obtained from 346 node-negative breast cancer patients showed improved 5 and 20-year survival rates with STAT3 activation." (PMID 38339245, 2024). "Studies have shown that PIKE-A activation of Akt binds to STAT3, stimulating FYN and inducing STAT3 phosphorylation, thereby enhancing G6PD transcription, activating PPP metabolism, promoting DNA and NADPH synthesis, and inhibiting ROS production, ultimately fostering tumor growth." (PMID 39624082, 2024). "Additionally, chronic inflammatory environments can also activate signaling pathways such as nuclear factor kappa B (NF-kB), signal transducer and activator of transcription 3 (STAT3), and hypoxia-inducible factor 1-alpha (HIF-1α) which promote cell survival and proliferation in tumour cells." (PMID 39516433, 2024). "Moreover, ISG15-depleted necroptotic DAMPs failed to induce NF-κB and STAT3 activation and tumor-cell EMT." (PMID 38926796, 2024). "In the HCC tumor microenvironment, chemokines and cytokines, such as stromal cell-derived factor 1 alpha (SDF-1α, CXCL12a) and IL-6, can induce MDSC infiltration and activation (IL-6/STAT3-mediated) to suppress the antitumor immune response and promote tumor progression." (PMID 38397901, 2024). "Given the key role of STAT3 signaling in cancer cell proliferation and survival, the question of whether the cell line-dependent regulation of this pathway could result in a divergent effect of LDHC silencing on tumor cell survival arose." (PMID 39001513, 2024). "Given that STAT-3 phosphorylation plays a key role in NK cell activity and function, STAT-3 phosphorylation was inhibited in the NK cells and the role of pGSN was investigated since NK cell-mediated tumor surveillance is enhanced in the STAT3 knockout mice model." (PMID 38891037, 2024). "A high level of histone lactylation in tumor-infiltrating myeloid cells induces METTL3 expression and m6A modification of Jak1 mRNA, which leads to the protein translation of Jak1 and the stimulation of downstream STAT3 signal that enhances myeloid immunosuppressive functions." (PMID 38200523, 2024). "Furthermore, STAT3's profound impact on the cellular inflammatory environment, highlighted by increased IL6 levels, may directly foster alterations in the tumor microenvironment, thereby affecting the phosphorylation and functional dynamics of LHPP." (PMID 39468431, 2024). "Our previous studies showed that anti-IL-6R antibodies potentially inhibited tumor growth and invasiveness in vitro and in vivo through interfering with IL-6 signaling transduction in IL-6R expressing CRC cell lines, including Erk-1/-2, STAT3 and AKT phosphorylation/activation." (PMID 38256960, 2024). "Additionally, cucurbitacin B can inhibit the JAK2/STAT3 signaling pathway, reduce the migration and invasion ability of M2-like TAM polarization-induced colon cancer cells, enhance the anti-tumor response, and increase the expression of CD4 and CD8 in the tumor microenvironment." (PMID 39275042, 2024).
tumor (continued). "The present study demonstrated that ART1 knockdown significantly inhibited IL-6-induced p-STAT3 and its target proteins, c-Myc, cyclin D1 and Bcl-xL (amp and E, 3 A-D, 7D & E), the proliferation of CRC cells and the growth of transplanted tumours in a mouse model." (PMID 38504172, 2024). "Additionally, we identified a negative correlation between GCSH expression and p-STAT3 in the tumor tissues of CCA patients using IHC." (PMID 38370386, 2024). "Once Tregs reach the tumor, differentiation/polarization and activation is induced by a variety of tumor- and immune-derived factors, including TGFβ, IL-10, PGE2/COX2, IL-35, adenosine, IL-6/STAT3, and even has_circ_0069313, a tumor-derived circular RNA that helps Tregs maintain FoxP3 levels." (PMID 38254801, 2024). "In normal tissues, lower p-STAT3 levels in Dnajb4+/+ mice compared to Dnajb4–/– mice suggest that the absence of HLJ1 may enable sustained tumor progression." (PMID 39738726, 2024). "In summary, we demonstrated that NASP promotes tumor progression and radioresistance and provides a plausible molecular mechanism involving ANXA2 phosphorylation and nuclear translocation, as well as enhanced STAT3 signaling, which promotes radioresistance and enhances tumorigenic behavior." (PMID 38605477, 2024). "As a result of decreasing STAT3 phosphorylation, CYTL1 could inhibit tumor metastasis." (PMID 39867879, 2024). "Additionally, we investigate the downstream effectors of TOP1 in CC cells and identify TOP1-mediated tumor-promoting inflammatory features, characterized by alterations in the expression of CXCLs, HMGB1, IL-6, and STAT3/5, as well as several T cell regulatory genes." (PMID 39156107, 2024). "Consequently, the constitutive STAT3 signaling imparted by the engineered IL-21R induced a unique phenotypic alteration in IL-21R-TCR-T, resulting in a “long-lived effector” phenotype following tumor stimulation." (PMID 38643203, 2024). "STAT3 exemplifies this problem, as efforts to understand its role of STAT3 in cancer have resulted in conflicting reports that show either a positive or negative role in tumor development." (PMID 38573819, 2024). "Furthermore, tumor cells in non-responders frequently showed heightened transcriptional activity in the NF-kB and STAT3 pathways, suggesting a potential inherent resistance to ICI therapy." (PMID 39514276, 2024). "In experiments with tumor-bearing mice, M.RGD@Cr-CTS-siYTHDF1 NPs, when exposed to laser irradiation, effectively killed tumor cells, disrupted the TME, delivered siYTHDF1 to TAMs, silenced the YTHDF1 gene, and shifted the STAT3-STAT1 equilibrium by reducing STAT3 and enhancing STAT1 expression." (PMID 38898486, 2024). "In addition to these pathways, other crucial pathways, such as STAT3, NF-κB, and PI3K, play a crucial role in influencing TAM activities, determining whether they promote or suppress tumor growth." (PMID 39796695, 2024). "SC144 did significantly reverse M-BMDM-promoted tumor growth with no observed inhibitory effects for LLC alone group, indicating that early SC144 treatment suppresses tumor growth mainly by interfering with IL-6/gp130/STAT3 cascade in M2 macrophages, but not in tumor cells." (PMID 38274367, 2024). "Additionally, NASP may activate the STAT3 pathway through p‐ANXA2, which, in turn, promotes radioresistance and tumor progression." (PMID 38605477, 2024). "Intriguingly, we found that PD‐L1 antibody monotherapy could induce phosphorylation of JAK1 and STAT3, thereby up‐regulating the expression of IRF1 and PD‐L1 in tumor tissues, which may also be one of the reasons why many patients are insensitive or resistant to PD‐L1 antibody monotherapy." (PMID 38953362, 2024). "By interacting with IL-6 receptor (IL-6R), IL-6 activates STAT3 by upregulating the expression of cyclin D1, D2, and B1, and c-Myc and downregulating the expression of the cyclin-dependent kinase (CDK) inhibitor p21, which collectively accelerates the entry of tumor cells into cell cycles." (PMID 38520006, 2024).
tumor (continued). "However, here we found that ISG15-RAGE-driven activation of NF-κB and STAT3 promotes the invasiveness and metastasis of peri-necroptotic cells, but not cell proliferation and primary tumor growth." (PMID 38926796, 2024). "Thus, while current inhibitors blocking YAP/TAZ-TEAD function might be effective against tumor angiogenesis, a more potent inhibition of tumor angiogenesis may be achieved by blocking complex formation between YAP/TAZ, AP1, and STAT3." (PMID 38538573, 2024). "Under high oxidative stress conditions within the tumor microenvironment, pancreatic ductal adenocarcinoma (PDAC) tumor cells secrete the KRAS G12D protein, which in turn stimulates fatty acid oxidation in macrophages and facilitates their polarization towards the M2-type through the STAT3 pathway." (PMID 38853203, 2024). "CD109 influences key inflammatory pathways, including TGF-β/NF-κB, EGF/STAT3, and various inflammatory cytokines like IL-6 and IL-8, impacting inflammatory processes such as immune cell recruitment, macrophage polarization, immune microenvironment, EMT, and tumor progression." (PMID 39990858, 2024). "The lncARSR could also interact with miR-34/miR-449 to upregulate the expression of signal transducer and activator of transcription 3 (STAT3) to induce the polarization of M2 macrophages in RCC, which may lead to tumor progression and metastasis due to immunosuppression function of M2 macrophages." (PMID 39296981, 2024). "However, most of these studies did not mention how the lncRNA/miRNA/STAT3 axis affects downstream signals and promotes tumor occurrence and development." (PMID 38172648, 2024). "In addition, IL-6 could also promote tumor cell survival, growth, proliferation, transformation, invasion, and migration by upregulating TGF-β and activating the STAT3 and HGF/c-MET pathways." (PMID 36831664, 2023). "Interestingly, NEDD9 can be significantly induced in tumor cells with high STAT3 levels, but not in tumor cells with low STAT3 levels." (PMID 37771106, 2023). "Moreover, to further investigate whether PepO inhibit M2 macrophage and tumor growth by inhibiting the JAK2-STAT3 pathway in vivo, colivelin was used to activate STAT3 in TNBC-bearing mice." (PMID 37925462, 2023). "Thus, we thought that lack of SIRPα exerted anti‐tumour effects possibly by increasing phagocytosis activity of MPs and NPs by suppressing STAT3 signalling." (PMID 36419386, 2023). "M-MDSC from 4T1 tumor-bearing mice with induced tumor site infiltration has been reported to promote tumor metastasis by inducing nitric oxide synthase 2 (NOS2) production and activating STAT1 and STAT3 signaling pathways in tumor cells to induce EMT and CSCs phenotypes." (PMID 37465670, 2023). "Moreover, this toxin also activates the signal transducer and activator of transcription 3 (STAT3) in intestinal epithelial cells, which leads to proliferation and apoptosis failure and drives chronic inflammation and tumor formation in an IL-17-dependent manner." (PMID 37555952, 2023). "Notably, compound 11c significantly reduced tumor growth by induced apoptosis in a mouse subcutaneous tumor implantation model in vivo, suggesting a potential for compound 11c to be further developed as a JAK/STAT3 signaling inhibitor for the treatment of cancer." (PMID 37103357, 2023). "Given that PI3K/Akt and JAK/STAT3 signaling pathways engaged in PTC tumor stromal-cell-enhanced CSC aggressive behaviors in vitro, we investigated whether these signaling pathways were relevant to PTC tumorigenesis and tumor progression." (PMID 36982542, 2023). "Consequently, we could conclude that the higher expression of STAT3, STAT4, STAT5A, STAT5B, and STAT6, the higher differentiation degree and less tumor stemness characteristics of BRCA tumor cells." (PMID 36968603, 2023). "Here, STAT4 overexpression inhibited tumor growth without STAT3 dependent in nude mice model." (PMID 38107057, 2023).
tumor (continued). "Therefore, the genetic relationship between STAT3 and PTEN may play an obligatory role in metastatic dissemination and tumor maintenance during therapy and progression." (PMID 37573301, 2023). "We could not find any evidence of tumor dissemination or metastasis in Ptenpc−/− Stat3C/+ mice up to > 52 weeks of age, which suggests that activated Stat3 plays a major role in preventing metastatic dissemination." (PMID 37573301, 2023). "Preclinical studies have demonstrated the efficacy of STAT3 pathway inhibitors, such as Stattic, C188-9, OPB-31121, OPB-51602, AZD9150, and STAT3 decoy oligonucleotide, as well as drugs targeting IL6/IL6R, including Siltuximab, Tocilizumab, and Olamkicept, across various tumor models." (PMID 37784157, 2023). "Inhibition of the STAT3 pathway and CCR6-CCL20 axis prevented Treg infiltration and inhibited tumor growth, thereby enhancing the radiosensitivity of HNSCC, and activating dendritic cells which reduced the growth of tumor cells that were resistant to radiotherapy." (PMID 37598158, 2023). "Therefore, results of the current study enhances the available understanding on tumor angiogenesis and shows that STK24/STAT3/VEGFA signaling pathway may be a novel therapeutic target for treatment of patients with NSCLC." (PMID 36720310, 2023). "Extending this work, the group later described that the MDSC-recruiting and protumorigenic features of FAP/STAT3/CCL2 signaling were conserved in iCCA, reiterating the importance of CAFs and FAP signaling in generating an immunosuppressive stroma that is permissive for tumor progression." (PMID 36708970, 2023). "Similarly, phosphorylated STAT3 in the nucleus enhances HIF-1α transcription, which in turn promotes the transcription of several proangiogenic genes such as VEGF, ultimately contributing to tumor angiogenesis." (PMID 36647454, 2023). "However, BF211 not only reduced tumor growth but also reduced the levels of p-JAK2 and p-STAT3." (PMID 36903477, 2023). "ANGPTL8 may be induced by STAT3 signalling, FFAs or other proinflammatory cytokines, such as TNF-α and TGFβ1, in the tumour microenvironment, and it may affect the differentiation and development of tumours through the following pathways." (PMID 38107478, 2023). "The elevated neutrophil-to-lymphocyte ratio in the TME during neoadjuvant chemotherapy could impair its anti-tumor efficacy due to upregulated neutrophil-CAFs-tumor cell IL-1β/IL-6/STAT-3 signaling, showing a poor/absent response." (PMID 37173915, 2023). "Additionally, multiple factors including drugs, proteins, RNA, and genes either positively or negatively regulate tumor cells proliferation, invasion, and apoptosis in OS by affecting the signaling pathways JAK/STAT3, Hippo, Wnt/β‐catenin, PD‐1/PD‐L1, Notch, MAPK, PI3K/AKT/mTOR, NF‐κB, and others." (PMID 37441462, 2023). "However, there is a controversy on this point as several other studies reported that inhibition, not activation, of the IL-6/STAT3 signalling pathway induced cellular senescence in tumour cells." (PMID 36825563, 2023). "Therefore, targeting STAT3 is an attractive strategy to alleviate MDSC-mediated immunosuppression in the tumour microenvironment without the need for myeloid cell depletion." (PMID 36161514, 2023). "Considering the dual role of STAT3 as either a pro-oncogene or tumor-suppressor, subject to the genetic background of the tumor, FNDC3B downregulation might induce upregulation of STAT3 phosphorylation and PTEN expression solely in U87MG cells treated with siFNDC3B constructed in this study." (PMID 38137388, 2023). "The role of STAT3 in GBM pathogenesis is still under debate, as it is unclear whether it is pro-oncogenic or tumor-suppressive, and recent reports suggest a feedback activation mechanism in STAT3, rather than inhibition, in response to the inhibition of the PI3K/Akt/mTOR signaling pathway." (PMID 38137388, 2023).
tumor (continued). "However, only in the context of FAK deletion did we observe inhibition of tumour growth and elevated granzyme-B expression indicative of CD8 T-cell engagement, implying that co-depletion of FAK and STAT3 is complementary through enhancing both CD8 T-cell infiltration and PDAC cell immunogenicity." (PMID 36977556, 2023). "The pro-tumor functions of IL-6 are mostly through IL6-STAT3 axis which triggers up-regulation of target genes responsible for tumor cell survival, the activation of STAT3 could also block the maturation of dendritic cells (DCs) and inhibit T cell function." (PMID 36875137, 2023). "Moreover, repressing STAT3 and HIF-1α could mitigate the tumor-promoting role of TRIM14 in HCC cells." (PMID 37628777, 2023). "In fact, IL-6 preferentially induced STAT3 phosphorylation across all C-GBM immune subsets, while STAT5 was favored in NC-GBM subsets, highlighting that inflammatory stimuli may have different immunomodulatory effects depending on tumor proximity to the LV." (PMID 37192001, 2023). "Genes regulated by other members of the STAT family, such as STAT3, were not significantly enriched in DEGs, suggesting that miR-145 exerted its anti-tumor functions mainly through STAT1/2 transcriptional factors rather than through other members of the STAT family." (PMID 37727442, 2023). "Furthermore, the results of DEGs and HALLMARK GSEA analysis showed that the FAP high expression was significantly correlated with EMT, cell junction, IL-6/STAT3, and TGF-β signaling pathway and chemokine releasing, which further suggests its immune suppressive role and close interaction with tumor." (PMID 37046312, 2023). "Additionally, siRNA knockdown of STAT3 suppressed M2 genes and promoted most of the M1 genes compared to miR-ctrl, which reprogrammed M2 macrophages polarized toward the tumor-suppressive M1 phenotype (*** p < 0.001; NS, not statistically significant)." (PMID 38001876, 2023). "Without the signalling activity of STAT3, pancreatic CSCs’ ability to form tumour spheres and maintain stemness is reduced, as was observed in the stemness model, designated to evaluate the role of p21-activated kinase 4 in the maintenance of stem cell features." (PMID 37108193, 2023). "In contrast, blocking JAK/STAT3 signaling with AZD1480 treatment barely had effects on the CSC invasive activity regardless of whether PDX or patient primary tumor stromal cells were involved in the invasion assays." (PMID 36982542, 2023). "Similarly, hsa-miR-23a-3p seems to enhance tumor and vascular growth in CRC via the Signal Transducer and Activator of Transcription 3/miR-23a-3p/Semaphorin 6D (STAT3/miR-23a-3p/SEMA6D) axis induced by Interleukin-17C (IL-17C), which also leads to VEGF production." (PMID 37444431, 2023). "Moreover, Apatinib inhibits the upstream of STAT3, vascular endothelial growth factor receptor-2 (VEGFR2), to decrease PD-L2 expression through the RhoA-ROCK-LIMK2 axis, eventually, suppressing tumour migration, invasion, and cytoskeletal rearrangement in osteosarcoma." (PMID 36522474, 2023). "Since ATXN3 promotes PD-L1 expression through STAT3 and HIF-2α, it will be interesting to test whether ATXN3 inhibition synergizes with STAT3- and HIF-2α–specific inhibitors in suppressing tumor growth, which could provide useful insights in translational studies." (PMID 38038129, 2023). "Furthermore, by modulating the IL-6/JAK2/STAT3 signal pathway, FTO and APOE may limit the glycolysis of PTC, which could ultimately affect the growth of the tumor." (PMID 36831377, 2023). "The results showed that knockdown of STAT3 expression by siRNA decreased RKO cell proliferation, but increased the expression of chemokines and proinflammatory factors and completely reversed the CMTR1-mediated induction of tumor cell proliferation and immune responses." (PMID 37024465, 2023).